PYY (peptide YY)
Diseases named in the same sentence as PYY in open-access papers (continued):
Sharing a sentence is not in itself a finding about the gene and the disease.
infection (5 papers, 2013 to 2024). The state of being infected such as from the introduction of a foreign agent such as serum, vaccine, antigenic substance or organism. "The findings attest to an important role of NPY and PYY in orchestrating homeostatic reactions to infection and immune stimulation." (PMID 23992467, 2013). "In addition, combined deletion of NPY and PYY aggravates and prolongs the weight loss caused by Bacille Calmette–Guérin, which attests to an important role of NPY and PYY in orchestrating homeostatic reactions to infection and immune stimulation." (PMID 29213271, 2017). "Infection can affect the ENS and potentially alter regulating gut and brain peptides and hormones like peptide YY (PYY), glucagon-like peptide-1 (GLP-1), cholecystokinin (CCK), leptin, or ghrelin." (PMID 39066248, 2024). "Although it must not be neglected that developmental compensations may mask the full implication of PYY and NPY, our results attest to an important physiological role of NPY and PYY in orchestrating multiple homeostatic reactions in the face of infection and immune stimulation." (PMID 23992467, 2013).
gastroenteropathy (2 papers, 2013 to 2023). "The accumulated data regarding the changes in PYY in gastrointestinal disorders could bebeneficial in clinical practice." (PMID 23292145, 2013).
gastrointestinal disease (2 papers, 2013 to 2023). A disease that occurs in the gastrointestinal system, excluding the hepatobiliary system. "Peptide YY (PYY) is affected in several gastrointestinal diseases and disorders." (PMID 23292145, 2013). "These functions regulated by PYY aredisturbed in several gastrointestinal diseases and disorders." (PMID 23292145, 2013). "It is not surprising, therefore,that abnormalities in PYY have been reported in gastrointestinal diseases and disorders." (PMID 23292145, 2013). "Ontological studies haveshown PYY cells appear early in the gastrointestinal tract of the embryo.Although PYY cell density is not affected by aging, it is abnormal in several gastrointestinal diseases anddisorders." (PMID 23292145, 2013).
bacterial infection (1 paper, 2023). "Therefore, the aim of our study was to estimate the impact of the severity of the disease and the type of bacterial infection in CF patients on the serum level of appetite-regulating hormones including leptin, ghrelin, NPY, ASP, POMC, KISS, PYY, and α-MSH." (PMID 37111072, 2023). "In addition, we found that neither the severity of the disease nor the type of bacterial infection affects the level of other tested hormones that regulate appetite (ghrelin, NPY, ASP, POMC, KISS, PYY, and α-MSH)." (PMID 37111072, 2023).
cardiovascular disease (1 paper, 2020). "Relevance of PYY in the context of cardiovascular disease has not been explored." (PMID 33291235, 2020).
PYY also shares sentences with these, for which no sentence is quoted: Hypercholesterolemia (3 papers); polycystic ovary (3); binge eating disorder (2); colorectal (2); acute leukemia (1); acute pancreatitis (1); bipolar disorder (1); brain disorder (1); Cachexia (1); cardiac hypertrophy (1); chronic kidney disease (1); cognitive decline (1); dumping syndrome (1); endocrine disorders (1); endothelial dysfunction (1); food allergy (1); fungal infections (1); gastric cancer (1); Gastrointestinal dysmotility (1); gastrointestinal infection (1); Glucose intolerance (1); Impaired glucose tolerance (1); intestinal disease (1); kidney disease (1); liver cirrhosis (1); liver fibrosis (1); liver inflammation (1); multiple sclerosis (1); musculoskeletal disorders (1); obstructive sleep apnea (1).
A further 7 diseases each share a sentence with PYY in 1 paper.